JAK2 (Janus kinase 2)
Diseases named in the same sentence as JAK2 in open-access papers (continued):
Sharing a sentence is not in itself a finding about the gene and the disease.
tumor (continued). "Furthermore, we investigated the contribution of IL-6, IL-8 and the JAK2/STAT3 signaling pathway to the pro-tumor effect of GC-MSC-primed macrophages." (PMID 31801938, 2019). "Activation of JAK2/STAT3 signaling may serve as the main mechanism that drives tumor progression of low expression of lincRNA-p21 in HNSCC." (PMID 30857539, 2019). "The effect of ZT55 on tumor cell proliferation was studied in 11 human cell lines of both hematologic and solid tumor origin, including HEL cells (harboring the JAK2V617F mutation), and TF-1 cells (carrying wild-type JAK2 but BCR-ABL-transformed)." (PMID 30717771, 2019). "These tumor inhibitory and tumor microenvironment normalizing effects of pacritinib could be attributed to the suppression of STAT3/JAK2 signaling." (PMID 31269723, 2019). "Additionally, local tumor cell density regulates cell density-dependent phenotypes through the synergistic signaling of IL-6 and IL-8 via the JAK2/STAT3 pathway." (PMID 30220965, 2018). "Aberrant JAK2/STAT3 signaling has been detected in a variety of tumor types, indicating that STAT3 inhibitors might to be widely effective as anticancer therapies." (PMID 30154439, 2018). "In this study, we show that local tumor cell density in 3D collagen I matrices regulates the expression and activity of MMPs through the synergistic paracrine signaling mechanism between IL-6 and IL-8 via the JAK2/STAT3 pathway." (PMID 30220965, 2018). "The JAK2/STAT3 signaling pathway is closely related to tumor development." (PMID 30271456, 2018). "Of these, prominent examples included amplifications targeting the epidermal growth factor receptor (EGFR) (7p11.2) and MYC (8q24.3) and deletions at 10q23.31, encompassing the PTEN tumour suppressor gene in cold tumours and JAK2 (9p24.1) amplifications in hot tumours." (PMID 30104673, 2018). "Importantly, the impact of systemic JAK1/2 inhibition with a small molecule inhibitor (e.g., ruxolitinib) almost certainly differs from tumour-specific loss of functional JAK1 and/or JAK2 signalling." (PMID 29319049, 2018). "We thus propose that the development of JAK2-specific inhibitors may be advantageous as they would leave NK cell-mediated tumor surveillance intact." (PMID 30671064, 2018). "PARK2 can inhibit the JAK2/STAT3/VEGF signaling pathway, and also through association with other genes and protein–protein interactions, regulate the network of growth pathways, thus becoming a vital tumor suppressor." (PMID 29515107, 2018). "From these findings we speculated that inactivation of JAK2/STAT3 or Src/STAT3 signaling pathway may be critical for SFN-induced anti-tumor effects in GBM cells." (PMID 28054986, 2017). "Thus, JAK2 deletion is a potential mechanism to hide tumor cells from recognition by cytotoxic T cells, especially in the cases of CDC274 and PDCD1LG2 deletions." (PMID 28977839, 2017). "Interestingly, we observed increased activation of anti-tumor immune-related pathways (STAT4/JAK2 and Type-I IFN signaling) and inhibition of BCSC regulators (β-CATENIN and NF-κB pathways) in HGFL-RON signaling-deficient BCSCs compared to controls." (PMID 28938607, 2017). "Thus, we draw that QRHX played a more important role in inhibiting tumor growth by regulating TAMs in mice, which was found to be associated with the inhibition of inflammation and the CXCL12/CXCR4/JAK2/STAT3 signaling pathway." (PMID 28630636, 2017). "Furthermore, icaritin treatment clearly reduced the expression of p-STAT3 and p-JAK2 in the epithelium of the tumor compared with untreated control." (PMID 28085115, 2017). "In our series, high expression of JAK2 was also observed in tumor cells, which may indicate that JAK2 is a prognostic biomarker in PBL." (PMID 29029457, 2017).
tumor (continued). "Compared to mice treated with control agents, mice treated with a combination of gemcitabine and JAK2 inhibitor formed small-sized tumors and survived longer, and notably, the tumor stroma contained fewer activated PSCs and displayed alterations in collagen production and organization." (PMID 29144412, 2017). "However, both SSM2 and SSM3 tumor cells also express the activated forms of JAK2 and STAT3 in SHAM-operated mice." (PMID 27391074, 2016). "Inhibition of IL-6 or of downstream JAK2 blocked HFD-induced tumor progression." (PMID 27049717, 2016). "In the present study, however, copy number gains of JAK2 were not positively associated with expression of p-STAT3 in tumor cells." (PMID 27050074, 2016). "Inhibition of the JAK2/STAT3 pathway in PTEN-deficient prostate tumors led to senescence-associated cytokine network reprogrammed, and improved the efficacy of docetaxel-induced senescence by triggering a strong anti-tumor immune response." (PMID 26919108, 2016). "To explore whether JAK2 play a key role in the anti-tumor effects of icaritin on U266 cells, we treated U266 cells with icartin in the presence of TG101209-a selective JAK2 inhibitor." (PMID 25865044, 2015). "We hypothesized that the small-molecule Jak2 inhibitor (BMS-911543) would elicit anti-tumor activity against PDAC and decrease immune suppressive features of the disease." (PMID 26575024, 2015). "Such a drug combination may have the ability to synergize tumor suppression and Jak2/STAT5b pathway inhibition." (PMID 26084564, 2015). "Thus an important clinical question is the role of a tumor cell driven elevation in JAK2 and PD-1 ligands versus increases arising from immune cells in solid tissue cancers." (PMID 26317899, 2015). "Furthermore, Icaritin-treated hepatospheres lost tumor initiating capability and the IL-6Rs/Jak2/Stat3 axis of hepatospheres treated with Icaritin was also suppressed." (PMID 26376676, 2015). "We hypothesized that the functionally selective, small-molecule Jak2 inhibitor would elicit anti-tumor activity against PDAC and decrease immune suppressive features of the disease." (PMID 26575024, 2015). "Since both anchorage-independent tumor growth and invasion facilitate metastasis, our results suggest that aberrantly-activated Aurora A and JAK2 pathways may cooperate to promote tumor metastasis." (PMID 24930769, 2014). "For the first time, we demonstrate that while the tumor volumes are kept small as a result of paclitaxel treatment, populations of tumor cells within the residual tumors retain the activated JAK2/STAT3 pathway and are enriched in markers such as Oct4 and CD117." (PMID 24782986, 2014). "Additionally, it will be of interest to see if other Jak2 inhibitors produce a similar type fibrotic effect in GBM tumor models." (PMID 25162558, 2014). "This CCR7/JAK2/STAT3 signal pathway regulates tumor metastasis by E-cadherin-mediated tumor EMT." (PMID 25405202, 2014). "Aurora A and JAK2 kinases are involved in cell division and tumor cell survival, respectively." (PMID 24930769, 2014). "All these findings suggest JAK2/STAT3 pathway may play a crucial role in simvastatin-induced anti-tumor effects in RCC cells." (PMID 23690956, 2013). "Moreover, we showed that an ODC inhibitor, α-difluoromethylornithine (DFMO), significantly abrogated the proliferation of transformed BaF3 cells by JAK2 (V617F) in vitro and efficiently inhibited JAK2 (V617F)-induced tumor formation in nude mice." (PMID 23300995, 2013). "Further investigation of the underlying mechanism revealed simvastatin could exert the anti-tumor effects by suppressing IL-6-induced phosphorylation of JAK2 and STAT3." (PMID 23690956, 2013). "The advent of small molecule inhibitors has highlighted JAKs and their effectors as potential therapeutic targets and JAK2 translocation malignancies are prime candidates for selective inhibitor treatments which among JAK2mu neoplasia have been rewarded with but moderate success hitherto." (PMID 23372669, 2013).
tumor (continued). "In our study, the transplantation of Ba/F3 cells expressing c-Myc (T58A) into nude mice caused subcutaneous tumor formation; however, it failed to exhibit the same malignancy as cells expressing JAK2 (V617F)." (PMID 23300995, 2013). "Jak2 is a new target for tumor growth suppression due to its role in the activation of STAT3." (PMID 22792362, 2012). "Treatment of NSCLC lines with the JAK2 inhibitor ruxolitinib inhibits anchorage independent growth and slows xenograft tumor formation, suggesting that selected patients with NSCLC may benefit from treatment with JAK2 inhibitors in addition to TKI." (PMID 22319590, 2012). "It has also been shown that adding wild type JAK2 to cells carrying the mutated JAK2 allele restores the growth factor dependency, indicating that in this case it is in fact favorable if not necessary for tumor progression to lose the wild type allele." (PMID 21899760, 2011). "Cellular experiments have confirmed that in JAK2V617F-mutant cells, STAT3/5 phosphorylation, driven by oncogenic JAK2 activity, enhances PD-L1 promoter activity and PD-L1 protein expression, which inhibits T cell activity, downregulates antitumor immunity, and promotes tumor invasion." (PMID 41268532, 2025). "Indeed, large-scale sequencing efforts encompassing thousands of CRC specimens have not identified JAK2 p.V617F mutations in tumor tissue, suggesting that this alteration is exceedingly rare or potentially absent from primary colorectal carcinogenesis." (PMID 40842629, 2025). "Furthermore, bufothionine reduced the serum concentration of IL-6; suppressed the expressions of STAT3 phosphorylated in Tyr705 and Ser727 amino acids and JAK2 in tumor tissues; and also increased the expression of Atg5, Atg7, and LC3II in SMMC7721 cells and H22 tumors." (PMID 39339202, 2024). "Intrinsic mechanisms include JAK2/STAT3 signaling transduction and intracellular STAT3’s direct transcriptional regulation of genes associated with tumor progression, such as those promoting the differentiation and cytotoxic functions of tumor-specific T cells." (PMID 38920657, 2024). "JAK2 (Janus kinase 2; located on chromosome 9p24), MPL (myeloproliferative leukemia virus oncogene; located on chromosome 1p34), and CALR (calreticulin; located on chromosome 19p13.2) are specific somatic driver mutations that have been described in the major part of BCR-ABL–negative neoplasms." (PMID 38541232, 2024). "Thus, G-CSF may be linked to JAK2 and various cytokines and chemokines that, when influenced by stimulation of HER2 signaling, contribute to tumor progression, tumorigenesis, and poor prognosis in UTUC." (PMID 39739128, 2024). "Interestingly, miR-375 was found to be downregulated in GC tissues and could suppress tumor cell proliferation through Janus kinase 2 (JAK2) inhibition." (PMID 36844871, 2023). "JAK2/STAT3 pathway could act as key targets for screening anti-tumor drugs." (PMID 37716993, 2023). "The multiple pathways downstream of JAK2 and the fact that other growth factors and hormones can activate this pathway may explain why we did not observe a specific association by pJAK2 tumor expression." (PMID 36882838, 2023). "Therefore, oligomerization between JAK2 fusions and their endogenous JAK2 fusion partner may contribute to leukemogenesis by impairing the tumor-suppressive function of the WT JAK2 fusion partner." (PMID 35903543, 2022). "Moreover, lncRNAs are involved in tumor-associated immune regulation, and the IFN-associated lncRNA INCR1 binds hnRNPH1, thereby preventing it from negatively affecting the expression of neighboring genes PD-L1 and JAK2." (PMID 36118202, 2022). "Moreover, JAK2/STAT3 is also involved in tumor genesis and development." (PMID 35216134, 2022).
tumor (continued). "In addition, many of these DNA-binding JAK2 fusion partners can act as tumor-suppressors, and their DNA-binding domains may also function as oligomerization domains." (PMID 35903543, 2022). "Based on previous literature and our study, we speculated that psoralen inhibited the proliferation and migration ability of tumor cells, promoted apoptosis, and blocked the cell cycle by reducing the expression levels of four genes: JAK2, PIK3CA, PIK3CB, and PIK3CG." (PMID 36065261, 2022). "Furthermore, PTPN11 is published to be in complex with JAK2 upon cytokine-induction in tumor cells." (PMID 33247204, 2021). "Lastly, we examined the frequency of somatic copy number alterations (SCNA) associated with regulation of anti-tumor immune responses in pre-clinical and clinical studies: gains in MYC16, losses of PTEN17 and gains or losses in interferon pathway genes (PDCD1, STAT1, JAK1, and JAK2)." (PMID 34446728, 2021). "In addition, the inhibition of JAK2 diminishes the tumor number and growth." (PMID 33802575, 2021). "Interestingly, JAK2 may play a role in keeping the Th-1 cytotoxic answer against the tumor present by mediating the IL-12 signaling and thereby phosphorylating STAT4." (PMID 34948183, 2021). "Moreover, SSFH could prolong survival rate and inhibit tumor growth via JAK2/STAT5 signaling pathway in vivo." (PMID 34121564, 2021). "In PDAC, activation of JAK2/STAT3 cell signaling with the participation of REG3G was found to induce immunosuppression by limiting the antigenicity of tumor cells, suppressing CD8+ cell function, causing variable expression of Th2 cytokines and increasing the proliferation of tumor cells." (PMID 32488850, 2020). "Additionally, miRNA-375 may act as a tumor suppressor and regulate GC cell proliferation by targeting the JAK2 oncogene and janus kinases." (PMID 32206186, 2020). "Furthermore, the anti-tumor activities of type I IFNs can be limited by the activation of several survival pathways, such as the induction of the JAK2/STAT-3 pathway, the activation of nuclear factor kappa-beta (NF-κB) and the increased expression of the epidermal growth factor receptor (EGF-R)." (PMID 32967656, 2020). "However, upon JAK2 silencing, the primary tumor volume was consistently reduced following RT." (PMID 31511084, 2019). "Thus, the influence of JAK2 inhibition on the growth of tumor cells in PMBCL might be less than that of HL." (PMID 31707975, 2019). "However, robust recurrent tumor growth with enhanced JAK2/STAT3 activation and CSC-like phenotype was observed in all mice groups after termination of treatments, but was delayed significantly in the paclitaxel and momelotinib treated group compared to other treatment groups." (PMID 29682172, 2018). "This signalling results in PI3K, MAPK and JAK2 pathway activation, and has been found to promote cell proliferation, angiogenesis and metastasis in xenograft models where administration of an anti-IL-8 monoclonal antibody attenuated tumour growth and metastatic potential." (PMID 30263091, 2018). "Additionally, in one of the patients with a STAT3 mutation, we detected a 9p copy number gain containing JAK2 and a point mutation in the protein tyrosine phosphatase (PTP) PTPRK, a commonly deleted tumor suppressor shown to negatively regulate STAT3 in NKTCL19." (PMID 29674644, 2018). "Moreover, JAK2 activated STAT3 pathway has tumor promoting activity." (PMID 28977839, 2017). "Importantly, inhibition of Jak2 impairs tyrosine 78 phosphorylation and tumor growth in vivo." (PMID 29168692, 2017). "In addition, curcumin could inhibit JAK2 activity and reduce tumor spheres via inhibiting the JAK2/STAT3 signaling pathway." (PMID 27529277, 2016).
tumor (continued). "JAK/STAT signaling pathway genes including JAK2, known to be related to tumor migration through the epithelial-mesenchymal transition (EMT), were only amplified in clusters P1 and M, supporting the hypothesis that clones in these clusters might be under migration pressure." (PMID 25881093, 2015). "Thus genomic amplification of 9p24.1 may provide a selective tumor cell dependent increase in both JAK2 and immune checkpoint signaling." (PMID 26317899, 2015). "Therefore, we investigated whether the contribution of TrkB to tumor metastasis involved EMT induction through activation of the JAK2/STAT3 and PI3K/AKT pathways." (PMID 26515594, 2015). "Thus, because of its role in a number of processes that are critical for tumor maintenance and growth, Jak2 inhibitor therapy may be more efficacious than other targeted therapies for tumors in which Jak2 signaling is dys-regulated." (PMID 25162558, 2014). "Altogether, these data point to different tumor-associated factors (i.e., IL-10, IL-6, PGE2) exerting their suppressive effects at various stages of myeloid DC development through converging and communicating signaling elements encompassing the JAK2/STAT3 and p38-MAPK pathways." (PMID 24324467, 2013). "Mechanistically, both in vitro and in vivo data showed that MrEVs activate the Janus kinase 2/signal transducer and activator of transcription 3 (JAK2/STAT3) signalling pathway, thereby driving M2 polarisation and tumour malignancy." (PMID 42249590, 2026). "Mechanistically, FCGBP modulated the PIGR/JAK2/STAT3 signaling pathway, thereby exerting both anti-tumor and anti-CDDP resistance effects." (PMID 41560312, 2026). "Low miR-133b levels correlate with increased phosphorylation of STAT3 (p-STAT3) and deregulation of the JAK2/STAT3/Bcl-2 axis, thereby promoting cell survival and tumor progression." (PMID 41596525, 2026). "Compared to neoplasms with PDGFRA or PDGFRB rearrangements, MLN-eo-TK with JAK2 rearrangements have a higher rate of progression and are associated with a poorer prognosis." (PMID 41530508, 2026). "The free radical scavenging potential of Salvia coccinea and apigenin is responsible for reduced oxidative stress and tumor cell metastasis modulated through PARP-cleavage, caspase-3, ERK, CDK-1, JAK2/STAT3, Bax/Bcl-2, AMPK, and Wnt/β-catenin pathways." (PMID 41640995, 2026). "CircNOL10 inhibits mammary tumorigenesis via miR-767-5p-dependent SOCS2 upregulation, which blocks JAK2/STAT5 signaling, thereby impairing tumor growth and metastatic dissemination." (PMID 41601694, 2026). "Ferulic acid suppresses tumor growth by inhibiting the PI3K/AKT and JAK2/STAT6 pathways, thereby promoting apoptosis (in vitro and in vivo)." (PMID 42193064, 2026). "The molecular mechanisms underlying these effects were further explored by focusing on the JAK2/STAT3 signaling axis, which has been shown to play a critical role in tumor cell migration, invasion, and metastasis." (PMID 40075566, 2025). "The results of WB show that the phosphorylation levels of JAK2 and STAT3 in the subcutaneous tumor tissues were significantly downregulated." (PMID 39852843, 2025). "By downregulating PRLR, Osthole disrupts the ligand-dependent activation of JAK2, leading to reduced STAT3 phosphorylation — a critical event in tumor cell proliferation and resistance to apoptosis." (PMID 40978029, 2025). "Building upon the understanding that leptin facilitates the migration and invasion of cancer cells through the JAK2/STAT3 signaling pathway, we investigated the influence of leptin within OB EVs on these critical stages of tumor metastasis." (PMID 40485730, 2025). "The JAK2/STAT3 signaling pathway is critical in angiogenesis-related disorders, with STAT3-dependent VEGF expression reported in human tumor cells." (PMID 40426248, 2025).